KMT2A (lysine methyltransferase 2A)
Diseases named in the same sentence as KMT2A in open-access papers (continued):
Sharing a sentence is not in itself a finding about the gene and the disease.
acute myeloid leukemia (continued). "MLLT4, also known as AF6, commonly fused with KMT2A in acute myeloid leukemia." (PMID 35650238, 2022). "Chromosomal translocations of the lysine methyltransferase 2A (KMT2A) gene produce KMT2A fusion proteins such as KMT2A-AFF1 (previously MLL-AF4), causing poor prognosis acute lymphoblastic leukemias (ALLs) that sometimes relapse as acute myeloid leukemias (AMLs)." (PMID 34088716, 2021). "Among the transcriptional dependencies that sustain leukemic identity in acute myeloid leukemia (AML), the menin-KMT2A chromatin complex has emerged as a central regulatory node." (PMID 42278415, 2026). "KMT2A rearrangements are identified in approximately 10% of cases of acute myeloid leukemia (AML) that occur across all age groups and represent distinct genetically defined types of AML." (PMID 40149468, 2025). "Dysregulation of the menin-KMT2A and polycomb repressive (PRC1/2) complexes in MLL-rearranged and NPM1-mutated acute myeloid leukemia (AML) contributes to the aberrant expression of self-renewal genes in hematopoietic stem and progenitor cells." (PMID 39607901, 2025). "KMT2A::CBL is a rare fusion of unknown pathogenesis generated by a unique interstitial deletion of chromosome 11 that has been reported across a wide age range in both acute myeloid leukemia (AML) and acute lymphoblastic leukemia (ALL) patients." (PMID 38643442, 2024). "Rearrangements involving the KMT2A/MLL gene are recurrently occurring in adult acute myeloid leukemia (AML) and constitute a defining genetic abnormality in the fifth edition of the WHO classification." (PMID 39766070, 2024). "The mixed-lineage leukemia 1 (MLL1) gene (lysine [K]-specific methyl transferase 2A (KMT2A)) located on chromosome 11q23 is disrupted in acute myeloid leukemias (AML), with more than 80 different KMT2A fusion partner genes described to date." (PMID 39354505, 2024). "KMT2A PTD was detected in 35 patients with acute myeloid leukemia (AML) (7%), 5 patients with myelodysplastic syndrome (MDS) (2.2%), and 5 patients with chronic myelomonocytic leukemia (CMML) (7.1%)." (PMID 39766092, 2024). "KMT2A partial tandem duplication (PTD) involves intragenic duplications within the KMT2A gene and has been associated with acute myeloid leukemia (AML) and myelodysplastic syndrome (MDS)." (PMID 39766092, 2024). "Chromosome translocations involving mixed lineage leukemia (MLL, also known as MLL1 or KMT2A) gene cause ~75% of infant and ~10% child/adult acute leukemias, characterized to be either acute myeloid leukemia (AML) or acute lymphocytic leukemia (ALL) 1-3." (PMID 34373735, 2021). "Menin scaffolds the oncogenic histone-lysine-N-methyltransferase (KMT2A)-fusion protein (FP) complex in KMT2A-r and wild-type KMT2A complex in NPM1-m acute myeloid leukemia (AML)." (PMID 41959134, 2026). "With more than 100 translocation partners, KMT2A rearrangement (KMT2A-r) can lead to ALL, acute myeloid leukemia (AML), and mixed phenotypic acute leukemia (MPAL), with dismal prognosis across all categories." (PMID 40584390, 2025). "More than 135 fusion partners for KMT2A have been identified in acute lymphoblastic leukemia (ALL) and acute myeloid leukemia (AML)." (PMID 39179671, 2024). "RVB is classified as a pioneering menin inhibitor and is currently being developed to treat relapsed or refractory (R/R) KMT2A-rearranged acute leukemias, which include both acute myeloid leukemia (AML) and acute lymphoblastic leukemia (ALL), as well as NPM1-mutant AML." (PMID 39768795, 2024). "Of the cases of BRAF V600E-mutant acute myeloid leukemia (AML) that have been described, most display monocytic morphology and concurrent KMT2A rearrangement." (PMID 39596583, 2024). "In pediatric acute myeloid leukemia (AML), fusions involving lysine methyltransferase 2A (KMT2A) are considered hallmarks of aggressive AML, for whom the development of targeted specific therapeutic agents to ameliorate classic chemotherapy and obtain a complete eradication of disease is urgent." (PMID 35153769, 2021).
acute myeloid leukemia (continued). "The chromosomal translocations of the mixed lineage leukemia (MLL, KMT2A) gene are found in both acute myeloid leukemia (AML) and acute lymphoid leukemia (ALL)." (PMID 32517300, 2020). "Rearrangements involving KMT2A have been shown to occur in precursors in B-acute lymphoblastic leukemia (B-ALL), T-acute lymphoblastic leukemia (T-ALL), acute myeloid leukemia (AML), myelodysplastic syndrome (MDS), mixed-lineage (biphenotypic) leukemia (MPAL), and secondary leukemia." (PMID 39272922, 2024). "Balanced rearrangements involving the KMT2A gene (KMT2Ar) are recurrent genetic abnormalities in acute myeloid leukemia (AML), but there is lack of consensus regarding the prognostic impact of different fusion partners." (PMID 38965370, 2024). "We select six representative genes from CancerMine, which include three most frequently reported genes in the context of acute myeloid leukemia (AML), KMT2A, FLT3, and MLLT3, as well as three genes that are least reported in this specific cancer, namely ZFP36L2, ZIC2, and ZNF582." (PMID 38431735, 2024). "MLL/KMT2A rearrangement constitutes more than 70% of infant acute lymphoblastic leukemia (ALL), ~35–50% of infant acute myeloid leukemia (AML), and 5–10% of adult AML cases." (PMID 39594699, 2024). "In acute myeloid leukemia (AML), the so-called master transcription factors such as RUNX1, KMT2A, and HOX are frequently disrupted by chromosomal translocations, resulting in neomorphic oncogenic fusion genes." (PMID 38201282, 2023). "Chromosomal rearrangements of the mixed-lineage leukemia (MLL, KMT2A) gene are recurrently found in a subset of acute lymphoblastic leukemia (ALL), acute myeloid leukemia (AML), and acute leukemia of ambiguous lineage." (PMID 34321607, 2022). "Ten patients with acute myeloid leukemia (AML) harboring KMT2A CNV had a complex karyotype, a negative prognostic factor in AML." (PMID 35688861, 2022). "The prevalence of KMT2A gene rearrangements is bimodal with translocations found in up to 80% of infants (diagnosed at less than 1 year of age) with acute lymphoblastic leukemia (ALL) and in young to middle-aged adults with acute myeloid leukemia (AML)." (PMID 35677155, 2022). "KMT2A::AF9+ cell culture samples strongly clustered with gene expression programs found in primary human AML samples and were even more closely related to the pediatric cohort rather than the adult acute myeloid leukemia." (PMID 38201282, 2023).
acute leukemia (206 papers, 2006 to 2026). A clonal (malignant) hematopoietic disorder with an acute onset, affecting the bone marrow and the peripheral blood. "Comparing different KMT2A translocations in the future will help to unravel the basic mechanisms of cell fate reprogramming of this particular group of high-risk acute leukemia patients." (PMID 41145673, 2026). "Revumenib received approval in 2024-2025 for relapsed or refractory KMT2A-rearranged acute leukemia and NPM1-mutated AML." (PMID 41749890, 2026). "KMT2A gene rearrangement (KMT2Ar) is associated with a type of malignant acute leukemia that has a poor prognosis and high relapse rate." (PMID 40430547, 2025). "Menin inhibitors represent a novel class of targeted therapies for acute leukemias driven by KMT2A rearrangements or NPM1 mutations." (PMID 41464798, 2025). "Lysine [K] methyltransferase 2A (KMT2A, previously known as MLL) gene rearrangements are common in acute leukemias of various lineages and are associated with features such as chemotherapy resistance and rapid relapse." (PMID 38643442, 2024). "The interaction between menin and MLL1 has been implicated in the development of acute leukemias driven by MLL1/KMT2A rearrangements (MLL1-r), NPM1 mutations (NPM1-mut), and NUP98 rearrangements (NUP98-r)." (PMID 39276940, 2024). "Commonly involved in acute leukemias of myeloid, lymphoid, and mixed lineages, KMT2A rearrangements encode KMT2A fused with a highly diverse range of partner genes." (PMID 38643442, 2024). "Acute leukemias with rearrangement of the Lysine Methyltransferase 2A (KMT2A, also known as MLL1) gene belong to the adverse risk group and are predominantly found in pediatric cases but also in adult acute lymphoblastic and myeloid leukemias (AML)." (PMID 39834944, 2024). "Herein, we present an updated ‘KMT2A recombinome 2023’ associated mainly with acute leukemia, ALL and AML." (PMID 37019990, 2023). "Chromosomal rearrangements involving the human KMT2A gene (NM_001412597.1) are recurrently associated with the disease phenotype of acute leukemias." (PMID 37019990, 2023). "Germline and somatic KMT2A variants are, respectively, associated with WDSTS and multiple neoplastic diseases, along with gene structural rearrangements that are common in acute leukemia." (PMID 35163737, 2022). "Here, we will discuss the normal biological roles of menin in acute leukemia, notably in KMT2A translocations and NPM1 mutation, as well as current drug development." (PMID 36497385, 2022). "Recent studies have also demonstrated the application of next-generation sequencing (NGS) technologies for the detection of KMT2A-r, which also facilitates the identification of numerous genomic alterations for risk classification of acute leukemia." (PMID 35734412, 2022). "Chromosomal rearrangements involving the KMT2A (MLL) gene are recurrently associated with the disease phenotype of acute leukemia." (PMID 35734412, 2022). "The KMT2A (MLL) gene rearrangements (KMT2A-r) are associated with a diverse spectrum of acute leukemias." (PMID 35734412, 2022). "Chromosomal translocations involving 11q23 where the lysine methyltransferase 2a gene (KMT2A) is located cause acute leukemias with high rates of resistance and relapse following standard treatments." (PMID 34588432, 2021). "Infant acute leukemia is frequently associated with translocations involving the KMT2A gene at 11q23, with approximately 40–60% of infants with AML harboring KMT2A rearrangements (e.g., MLL-ENL, MLL-AF4, or MLL-AF9)." (PMID 33668444, 2021). "The mixed-lineage leukemia (MLL) protein has been studied in detail due to the dysregulation of gene expression caused by the rearrangement of the MLL1 (KMT2A) gene in acute leukemia." (PMID 34201935, 2021). "Through this approach, we have discovered three novel KMT2A translocation partners in childhood acute leukemia—genes encoding tyrosine kinase BTK, ubiquitin-protein ligase PRPF19, and NUTM2A—gene of poorly known function." (PMID 34440129, 2021).
acute leukemia (continued). "Chromosomal rearrangements of the human KMT2A/MLL gene are associated with acute leukemias, especially in infants." (PMID 34440129, 2021). "Activating signaling mutations are common in acute leukemia with KMT2A (previously MLL) rearrangements (KMT2A-R)." (PMID 29720585, 2018). "KMT2A‐rearrangements occur in about 10% of acute leukemia patients and are associated with a particularly poor prognosis, while NPM1mut are present in about 30% of patients with acute myeloid leukemia and are linked to relatively favorable outcomes after chemotherapy." (PMID 40181550, 2026). "Over the last decades, the KMT2A recombinome has been unraveled and currently exhibits 107 direct KMT2A fusions (KMT2A::X), 16 out-of-frame fusions to partner genes, and 16 reciprocal KMT2A fusions (X::KMT2A), all associated with the development of acute leukemia in patients." (PMID 41145673, 2026). "To date, revumenib stands as the most clinically developed small molecule menin inhibitor, demonstrating promising results in the first in-human phase I/II clinical trials including relapsed or refractory pediatric and adult KMT2A-rearranged or NPM1-mutated acute leukemia patients." (PMID 38892207, 2024). "These collective findings underscore the potential significance of menin inhibitors as crucial therapeutic targets for patients with KMT2A-mutated acute leukemia, with ongoing evaluation of combinatorial strategies offering promising avenues for further exploration and potential clinical benefit." (PMID 38673842, 2024). "KMT2A-rearrangements define a subclass of acute leukemias characterized by a distinct gene expression signature linked to the dysfunctional oncogenic fusion proteins arising from various chromosomal translocations involving the KMT2A (also known as MLL1) gene." (PMID 39834944, 2024). "MLL1 (KMT2a) gene rearrangements underlie the pathogenesis of aggressive MLL-driven acute leukemia." (PMID 33562706, 2021). "In acute leukemia with KMT2A rearrangements (KMT2A-R), activating signaling mutations are common." (PMID 29720585, 2018). "The most frequently found fusion partners of KMT2A in acute leukemia are the C‐terminal parts of AFF1, MLLT3, MLLT1 and MLLT10." (PMID 39887730, 2026). "Menin inhibitors are the first targeted therapies for KMT2A-rearranged and NPM1-mutated acute leukemias, addressing a significant unmet need in these high-risk subtypes." (PMID 41749890, 2026). "Acute leukemias involving KMT2A (MLL) rearrangements are aggressive hematologic malignancies associated with a poor prognosis, especially in infants." (PMID 42001795, 2026). "Acute leukemias initiated by rearrangement and fusion of the KMT2A (MLL) gene to a variety of partners are among the hematologic malignancies with the worst prognoses." (PMID 40898981, 2026). "Menin inhibitors target the Menin-KMT2A interaction, which is critical for leukemogenesis in KMT2A-rearranged acute leukemia." (PMID 41335282, 2025). "The binding of KMT2A fusion proteins to menin plays a crucial role in activating transcription pathways involved in KMT2Ar acute leukemia." (PMID 40430547, 2025). "Another target for acute leukemias is the histone–lysine N-methyltransferase 2A (KMT2A) gene, previously referred to as the MLL (mixed-lineage leukemia or myeloid/lymphoid) gene, which can undergo translocations with different partner genes." (PMID 39858509, 2025). "Currently, menin inhibitors are in clinical development for acute leukemia with KMT2A gene rearrangement." (PMID 39859151, 2025). "Both MLL-r and NPM1c acute leukemias demonstrate a strong dependency on KMT2A complex-chromatin binding to maintain high leukemogenic gene expression and promote cellular self-renewal." (PMID 39607901, 2025).
acute leukemia (continued). "Revumenib became the first FDA-approved menin inhibitor based on results from the AUGMENT-101 study, which demonstrated an overall response rate of 68% in heavily pretreated KMT2A-rearranged acute leukemia patients." (PMID 41464798, 2025). "Rearrangements involving KMT2A occur in ~10% of acute leukemias, with high prevalence in infant ALL (>70%) and involvement of over 100 fusion partners." (PMID 40710017, 2025). "The KMT2A breakpoint cluster primarily localizes between KMT2A exon 9 and intron 11, covering 93.5% of breakpoints in acute leukemia." (PMID 40707674, 2025). "Menin inhibitors that target KMT2A-r acute leukemias are currently being studied, and revumenib was recently approved for relapsed/refractory (R/R) acute leukemias with KMT2A translocations in both adult and pediatric populations for AML, ALL, and MPAL." (PMID 40584390, 2025). "Rearrangements of lysine methyltransferase 2A (KMT2A), located on chromosome 11q23, occur in 5–10% of pediatric and adult acute leukemias." (PMID 41290614, 2025). "In particular, acute leukemia with NPM1 mutations (NPM1m) and KMT2A rearrangements (KMT2Ar) represent the primary targets of this emerging drug class." (PMID 40710017, 2025). "These images utilized three different types of probes: enumeration probes, dual-fusion probes, and break-apart probes, corresponding to myelodysplastic syndrome (MDS), PML-RARA acute leukemia, and KMT2A gene acute leukemia, respectively." (PMID 40890868, 2025). "Bleximenib, for instance, is currently being tested in a pediatric cohort (12 years and older) of the phase 1/2 study (cAMeLot-1) for acute leukemia patients harboring KMT2A, NPM1, NUP98, or NUP214 alterations (NCT04811560)." (PMID 41154380, 2025). "Following a priority review of these data, the FDA approved revumenib as a treatment for KMT2A-rearranged acute leukemias in the relapsed or refractory setting while awaiting the final analysis for the NPM1-mutated AML subset." (PMID 40374809, 2025). "The interaction of menin with KMT2A and subsequent overexpression of HOX genes is responsible for the pathogenesis of acute leukemia with KMT2A-r." (PMID 40584390, 2025). "Menin plays a critical role in lysine methyltransferase 2A (KMT2A)-gene-rearranged and NPM1-m acute leukemias, both associated with adverse outcomes with current standard therapies, especially in the relapsed/refractory setting." (PMID 39594699, 2024). "MI has the potential to reach a more significant subset of acute leukemia with similar dependency as the menin–KMT2A interaction thanks to the improved precision approaches testing characteristic gene expression." (PMID 39594699, 2024). "In this scenario of rapid and interesting changes, menin inhibitors represent a novel class of drugs that have shown promising results in histone-lysine N-methyltransferase 2A (KMT2A)-rearranged (KMT2Ar) and in NPM1-mutated (NPM1mut) acute leukemias." (PMID 38651453, 2024). "The lysine methyltransferase 2A gene KMT2A (also known as MLL), located on chromosome 11q23, can be rearranged with different gene loci and can occur in acute leukemias of lymphoid or myeloid origin." (PMID 38473221, 2024). "There are at least six distinct menin‐KMT2A inhibitors that are currently being evaluated in clinical trials as first‐ and second‐line monotherapy for acute leukemias (DSP‐5336, BMF‐219, DS‐1594, JNJ‐75276617, ziftomenib, and revumenib)." (PMID 39428967, 2024). "Previous studies showed synergistic effects by combining the predecessor of revumenib, SNDX-50469 (VTP50469), with a DOT1L inhibitor in both KMT2A-rearranged and NPM1-mutated acute leukemia." (PMID 38892207, 2024). "Numerous genomic breakpoints within the KMT2A gene have been reported in young children and adults with hematologic disorders and are present in up to 10% of acute leukemias." (PMID 39201709, 2024).